IGFBP2 (insulin like growth factor binding protein 2)
Diseases named in the same sentence as IGFBP2 in open-access papers (continued):
Sharing a sentence is not in itself a finding about the gene and the disease.
tumor (continued). "They further performed a biomarker study for LRRC19 > IGFBP2, with a total of 47 patient tumor tissues from 10 different sites." (PMID 32316597, 2020). "Our results indicate that the tumor-growth promoting function of ASCs is influenced by the balance of IGF1/IGFBP2." (PMID 32133294, 2020). "IGFBP1/2/4/5/6 are useful prognostic predictors for chemotherapeutic effect in OC patients, and IGFBP2/4 are potential tumor markers for the diagnosis of OC." (PMID 33282953, 2020). "Often, IGFBP2 expression positively correlates with tumor aggressiveness and other known cancer markers." (PMID 31296788, 2019). "It has been reported that Insulin-like growth factor (IGF) binding protein 2 (IGFBP2) is associated with the mobility and invasion of tumor cells." (PMID 31138764, 2019). "IGFBP2-driven tumors are dependent on the continued expression of IGFBP2, as knockdown led to a significant decrease in tumor progression and prolonged survival." (PMID 31296788, 2019). "Blocking IGFBP2 suppressed tumor growth and improved survival of tumor bearing mice in the mouse GBM model." (PMID 31560714, 2019). "IGFBP2 (Insulin-like growth factor binding protein 2), an important member of the Insulin-like growth factor binding protein family, modulates cell growth, differentiation, migration, and invasion in neoplasms." (PMID 31130992, 2019). "To better elucidate the role of MMP‐1/IGF2/IGFBP2 in MSC tumor tropism, we analyzed the expression of IGFBP2 in MSCs with different tumor‐tropic properties by western blot analysis." (PMID 29321953, 2018). "This proposed autocrine loop to promote angiogenesis and tumor progression is difficult to reconcile with our results showing that patients with increased IGFBP-2 during induction treatment seem to benefit from prolonged bevacizumab maintenance treatment." (PMID 30592740, 2018). "Collectively, these studies suggest that circulating IGFBP‐2 levels partly reflect tumor secreted protein." (PMID 29722920, 2018). "Most likely an up regulation of IGFBP-2 mirrors the hypoxic state of the tumor through HIF-1α, a master transcriptional regulator of the hypoxic response." (PMID 30592740, 2018). "Taken together, these results showed that the MMP‐1 secreted by highly tumor‐tropic MSCs cleaved IGF‐2/IGFBP2 complex." (PMID 29321953, 2018). "Circulating IGFBP2 levels correlated well with the tumor size (R = 0.241, P = 0.008), and IGFBP2 levels were significantly higher in larger tumors (> 6 cm) than those of smaller ones (956.8 ± 734.0 ng/ml vs. 548.6 ± 364.0 ng/ml; P = 0.007)." (PMID 28036255, 2017). "Higher serum IGFBP2 levels were likely to be found in large tumors and in higher tumor stages, presenting circulating IGFBP2 level as a marker for tumor burden, as previously indicated." (PMID 28036255, 2017). "On the other hand, removal of IL-10 inducing T cell epitopes from the insulin-like growth factor-binding protein 2 (IGFBP2) vaccine conferred potent anti-tumor activity." (PMID 28211521, 2017). "We observed that the silencing of Hsp27 decreases the IGFBP2 levels, consequently decreasing tumor proliferation, migration, and invasion, indicating the therapeutic importance of Hsp27 as a target for potentially increasing patient survival." (PMID 28903396, 2017). "The tumor suppressive functions of IGFBP-2 align with its ability to bind IGFs, while its oncogenic properties appear to be IGF-independent." (PMID 28977895, 2017). "On the basis of these results, an orthotopic tumor model was developed to further assess the tumor-promoting effect of IGFBP-2 and its in vivo effect on the sensitivity to gemcitabine." (PMID 28977895, 2017). "In other cellular models and tumor types IGFBP-2 has been shown to promote tumor growth and metastasis." (PMID 27200287, 2016). "Three human target genes of anti-Let-7 (HMGA2, LIN28B, and IGFBP2) were upregulated in both the tumor core and peripheral tumor region after ITu injection only." (PMID 27102443, 2016).
tumor (continued). "An engineered protease resistant IGFBP-2 inhibits MCF-7 tumour cell growth as a xenograft in a female nude Balb/c mouse model illustrating the importance of post-translational modification on the activity of IGFBPs." (PMID 27050076, 2016). "We stained the TMA slides with antibodies against IGFBP2 as well as with the epithelial marker cytokeratin in order to identify tumor cells." (PMID 26097693, 2015). "Because IGFBP2 has been shown to modulate both the IGF and integrin pathways and is a mediator of cell growth, invasion, and resistance in other tumor types, we evaluated the functional role of IGFBP2 in EAC progression and chemoresistance." (PMID 26317790, 2015). "The tumor suppressive functions of IGFBP2 align with its ability to bind IGFs while its oncogenic properties of IGFBP2 appear to be IGF-independent." (PMID 25774149, 2015). "Similar to IGFBP-1, studies examining the prognostic and predictive value of IGFBP-2 as a biomarker are conflicted and require further studies to clarify its value in specific tumor types." (PMID 26217584, 2015). "IGFBP2 has been demonstrated to have both tumour suppressive and oncogenic properties in different cancer types." (PMID 26107517, 2015). "Further there is significant evidence for a growth promoting effect of IGFBP-2 in many tumour systems, by sequestering IGFs." (PMID 25866791, 2015). "The influence of IGFBP-2 was stronger than that of CAA-CM probably because these media also contained other tumor suppressing factors which are able to inhibit the IGFBP-2-induced invasion of MCF-7 cells." (PMID 25747684, 2015). "In the future assessment of IGFBP2’s role in cancer, it will be important to consider (i) should IGFBP2 levels be assessed in plasma or the tumor/tumor microenviroment?" (PMID 25774149, 2015). "IGFBP2 has been shown to have both pro-tumourgenic properties and tumour suppressive functions, although the former tend to be independent of IGF/IGF receptor signalling." (PMID 26107517, 2015). "There was an increased amount of IGFBP-2 staining in both the tumor and surrounding adipose in the metastatic example." (PMID 25747684, 2015). "We quantified the areas of both IGFBP2 staining and cytokeratin staining (representing total tumor area), and calculated the percent IGFBP2 positive area per tumor area in order to normalize to the amount of tumor present in each sample (Datafile 2)." (PMID 26097693, 2015). "IGFBP2 and the other family members have been proposed to suppress tumor development through binding IGFs preventing binding to their receptor and thereby preventing IGF driven tumorigenesis." (PMID 25774149, 2015). "Evaluation of IGFBP2’s role in each group will then provide a better understanding of it oncogenic and tumor suppressive potential." (PMID 25774149, 2015). "Collectively, these results indicate that plasma IGFBP-2 in GBM patients has other origins besides the tumor." (PMID 24690948, 2014). "IGFBP-2 enhances tumor angiogenesis by promoting angiogenesis and facilitating the induction of VEGF-A in endothelial cells." (PMID 25000307, 2014). "For another thing, plasma IGFBP-2 levels were remarkably high in some radiologically tumor-free patients after combined therapy." (PMID 24690948, 2014). "Our interests lead us to further investigate IGFBP2 proteolysis in human glioma cancer cell lines and tumor samples." (PMID 24962328, 2014). "The intensity of this cleaved IGFBP2 form and its ratio with the full-length molecule in every tumor sample showed different proportions, suggesting diverse proteolytic activities." (PMID 24962328, 2014). "And it is assumed that elevation of the IGFBP-2 production is part of a mechanism to compensate for the mitogenic and antiapoptotic effects of tumor-derived IGFs." (PMID 23573145, 2013).
tumor (continued). "Unlike IGFBP3, which induces antitumor activity in different types of cancers, IGFBP2 has been shown to promote tumorigenesis, cancer cell invasion, metastasis, cancer stem cell expansion, and tumor angiogenesis in various types of cancers." (PMID 24069370, 2013). "The genes up regulated in IGFBP2 positive tumor samples showed significant enrichment in Focal adhesion, MAPK signaling pathway, apoptosis, Chemokine signaling, cytokine-cytokine receptor interaction and ECM receptor interaction and Wnt signaling pathway." (PMID 23767917, 2013). "IGFBP-2 has been widely studied in cancer research, where it was shown to be both inhibiting and stimulating for IGF-I linked tumor growth." (PMID 24359611, 2013). "Insulin-like growth factor-binding protein-2 (IGFBP-2) is considered to be a human tumor antigen, and the tumor-specific immunity of IGFBP-2 has been reported in several types of cancer." (PMID 23165420, 2013). "The blood IGFBP2 value was mildly but also significantly correlated with the tumor size (R= 0.21, P=0.023)." (PMID 24069370, 2013). "There was a positive correlation between IGFBP2 and β-catenin expression with 26 out of 27 IGFBP2 positive tumor samples also staining positive for β-catenin." (PMID 23767917, 2013). "It has been reported that IGFBP2 inhibits the IGF dependent proliferation of normal cells while in tumor cells, it promotes proliferation in an IGF1R dependent or independent manner." (PMID 23767917, 2013). "Univariate analysis showed that the survival is significantly correlated with histopathologies, disease stages, tumor sizes, and blood IGFBP2 levels (cutoff value at 160.9 ng/ml, which has the largest area under ROC curve)." (PMID 24069370, 2013). "Two out of 10 proteins (IGF-2R and IGFBP-2) were differentially expressed between tumor samples and matching paratumorous samples, with P-values of less than 0.05." (PMID 23071652, 2012). "IGF-2R and IGFBP-2 were then used to differentiate between tumor samples and matching paratumorous samples using unsupervised hierarchical cluster analysis." (PMID 23071652, 2012). "The expression of IGFBP-2 was in general higher in tumor tissue compared with matching paratumorous tissue." (PMID 23071652, 2012). "IGFBP-2 has been found to be a growth factor-promoting tumor, and elevated in the serum of patients with various malignancies." (PMID 23071652, 2012). "A number of biomarkers identified here are consistent with those reported in the literature in terms of their altered gene expressions in tumor tissues, including caveolin 1, cyclin B1, 14-3-3zeta, Stat5, activated p38, and IGFBP2." (PMID 22348039, 2012). "They purport that IGFBP2 probably plays a role in GBM tumor progression, and DNA-PK in the malignant transformation of glioma." (PMID 24212625, 2011). "PTEN also has an important role in CaP progression, and global expression profiling identified IGFBP-2 as the most significant biomarker for tumour PTEN status." (PMID 21487405, 2011). "An increased level of IGFBP-2 protein has been reported in liver tissues and serum during human malignancy with a positive correlation to the malignancy status of the tumor." (PMID 21205313, 2011). "We designed a his-tagged capture ELISA based on lysate from genetically engineered CHO cells for detection of antibodies to insulin-like growth factor binding protein 2, a novel tumor antigen." (PMID 18510754, 2008). "We tested the potential tumour marker characteristics of IGFBP-2 SDS against three endpoints: metastasis alone; local pelvic recurrence alone; and metastasis and recurrence combined." (PMID 11044360, 2000). "Within the malignant tissues IGFBP-2 mRNA levels correlated with the aggressiveness of the tumour and were higher in invasive tumours than in those with borderline pathology." (PMID 8624265, 1996). "IGFBP2 may promote tumor progression via the insulin-like growth factor (IGF) signaling pathway, although the precise molecular mechanisms warrant further exploration." (PMID 40115255, 2025).
tumor (continued). "It raises the question of whether IGFBP2 functions as an oncogene or a tumor suppressor in cases of upregulation versus downregulation." (PMID 39854135, 2025). "Furthermore, the same group showed that in a murine model of CRC, CD38/IGFBP-2-expressing fibroblasts promote tumor growth and survival via lowered immune cell activation." (PMID 41226289, 2025). "IGFBP-2 and 6 promote M2 polarization, promoting tumor progression, and knockdown mouse models identified a phenotype switch to pro-inflammatory M1 cells and reduced tumor growth." (PMID 41226289, 2025). "SCFAs promote tumor development and the expression of IGFBP2." (PMID 38778379, 2024). "Treatment with a neutralizing antibody against Igfbp2 decreased tumor growth in aged mice." (PMID 39007351, 2024). "High expression of IGFBP2 can help tumor macrophages to form an immunosuppressive microenvironment and exert a substantial inhibitory effect on T cell proliferation and activation, and this may be related to immunogenic death." (PMID 38378721, 2024). "Also, the recurrence period and overall survival of patients with high expression of IGFBP-2 in the tumor have been significantly shortened." (PMID 39138166, 2024). "In oncology, IGFBP-2 may assume a dual role, acting as an oncogene in a certain context and functioning as a tumor suppressor, depending on the cellular environment." (PMID 39585162, 2024). "However, in certain cancers, particularly when overexpressed, IGFBP-2 promotes tumor growth, invasion, and metastasis via IGF-independent mechanisms." (PMID 39585162, 2024). "Additionally, Western blot analysis of tumor lysates from aged mice treated with anti-Igfbp2 showed decreases in Fasn and p-Akt levels." (PMID 39007351, 2024). "Our analysis unveiled a notable overexpression of IGFBP-2 in tumor cells." (PMID 39138166, 2024). "Moreover, treating young mice with rIgfbp2 increased tumor growth, whereas neutralizing Igfbp2 decreased tumor growth." (PMID 39007351, 2024). "Because of its role in tumor progression, IGFBP2 has been investigated as a tumor biomarker." (PMID 39221034, 2024). "We next examined tumor lysates by Western blot analysis for downstream markers of Igfbp2 signaling." (PMID 39007351, 2024). "Interestingly, there were different expression patterns in the other areas, as CP as well as IGFBP2 were expressed more toward the cellular part of the tumor, whereas LOX was expressed more in the peripheral vascular zones." (PMID 38339384, 2024). "Furthermore, IGFBP-2 levels were positively correlated with tumor size and decreased significantly in patients following curative surgery." (PMID 38137390, 2023). "Tumor xenograft experiments were conducted using HepG2 cells with IGFBP2 overexpression and with vector control, and the results showed enhanced tumor progression in the group with IGFBP2 overexpression compared with the control group, as evidenced by the increased tumor weight and volume." (PMID 37957694, 2023). "Finally, we analyzed the expression of Igfbp2 in a heterogeneous tumor cell population in mouse SmoM1 mutant MB." (PMID 37029430, 2023). "A high level of IGFBP2 was positively correlated with tumor size, and organ metastasis." (PMID 37957694, 2023). "We observed IGFBP2 throughout the tumor, including in GFAP-positive astrocytes." (PMID 37029430, 2023). "Notably, elevated levels of IGFBP2 have been consistently observed in both the plasma and tumor cells of many patients with malignant tumors." (PMID 37957694, 2023). "Interestingly, UMAP of Smo mutant MB shows Igfbp2 expression in diverse cell types including astrocytes, fibroblasts, and tumor cells." (PMID 37029430, 2023). "However, other studies report that IGFBP2 promoted tumor cell proliferation, likely in an IGF-independent manner." (PMID 37374044, 2023). "Multiple studies have found that IGFBP2 plays different roles in different tumor angiogenesis." (PMID 38012763, 2023).
tumor (continued). "Further research was done on the possible tumor- and macrophage-promoting properties of IGFBP2." (PMID 37928523, 2023). "For example, IGFBP1 and IGFBP2 are closely related to human insulin sensitivity; IGFBP2 may inhibit the effective ways of tumor growth and metastasis." (PMID 37088808, 2023). "Also, the multiple functional domains of IGFBP-2 are thought to contribute to the spatial regulation of IGFBP-2 tumor biology, inducing different regulatory mechanisms operating in the extracellular, intracellular, and nuclear environments." (PMID 37946307, 2023). "Moreover, IGFBP2 overexpression is correlated with tumor cell proliferation, invasion, and migration." (PMID 35546443, 2022). "Previous studies also found that IGFBP2 could accelerate the migration of tumor cells by regulating LEF1 and SNAI2." (PMID 35519620, 2022). "ROC curve analysis showed that the addition of IGFBP‐2 and ‐3 biomarkers to a preoperative reference model comprising age, sex, and clinical tumor stage improved the discriminatory ability for prediction of LNM (+10.0%, P < 0.001), pT3/4 disease (+1.3%, P = 0.024), and any NOCD (+2.4%, P = 0.003)." (PMID 35368130, 2022). "Additionally, IGFBP2 increases Treg infiltration in the tumor microenvironment and promotes disease progression in mouse PDAC." (PMID 36556226, 2022). "For instance, GBC9-MT showed elevated expression of CD24 (immune checkpoint in promoting immune evasion) and IGFBP2 (metabolic checkpoint in promoting tumor growth), and GBC10-MT displayed cancer stem cell signature (OLFM4) and enhanced cell migration (e.g., CLDN3, CEACAM5)." (PMID 36198671, 2022). "Jointly, these observations indicated that high IGFBP2 expression by PDAC tumor cells induced T cell differentiation to promote an immunosuppressive TME, leading to higher amounts of Tregs and impaired cytotoxicity and proliferation of cytotoxic T cells by inducing apoptosis." (PMID 36556226, 2022). "High expression of IGFBP2 was detected in LGG tumor tissues compared with normal brain tissues." (PMID 35535221, 2022). "The proteins include GFAP, YKL‐40 and IGFBP-2, which are either cytoskeletal proteins in astroglial tumors, or overexpressed genes of the tumor cells that may be involved in tumorigenesis." (PMID 35673564, 2022). "Interestingly, a recent study reported that silenced IGFBP2 acts as a tumor suppressor gene in epithelial bladder cancer cells." (PMID 33498859, 2021). "Furthermore, a study showed that IGFB-1 and IGFBP-2 were downregulated in HCC tumor tissue compared with normal liver tissue, whereas IGFBP-4 was upregulated." (PMID 34452353, 2021). "IGFBP-2 is highly expressed in the serum and tumor tissues of most cancers." (PMID 34452353, 2021). "Interestingly, the vascular endothelial growth factor (VEGF) and insulin-like growth factor-binding protein-2 (IGFBP-2) in MCF-7 tumor cells exposed by mechanical stimulation was expressed more than in those without stimulation." (PMID 32150989, 2020). "Interestingly, the VEGF and IGFBP-2 in MCF-7 tumor cells exposed by mechanical stimulation was expressed more than in those without stimulation." (PMID 32150989, 2020). "Moreover, tumor cells from this stage IV sample show upregulation of genes related to EMT, angiogenesis, and metabolic pathways, including those that have been previously associated with tumor progression such as MMP1, S100A2, TSPAN8, and IGFBP2." (PMID 33170151, 2020). "IGFBP2 is overexpressed in many tumors, especially in blood vessel growth into large tumors, and IGFBP2 expression levels are highly correlated with grade of malignancy and poor tumor differentiation." (PMID 33019943, 2020). "Herein, we have explored the value of IGFBP2 as tumor antigen, evaluating whether IGFBP2 autoantibodies can be used either as diagnostic or prognostic biomarkers for RMS patients." (PMID 32093404, 2020).